SPOP (speckle type BTB/POZ protein)
Diseases named in the same sentence as SPOP in open-access papers (continued):
Sharing a sentence is not in itself a finding about the gene and the disease.
colorectal cancer (25 papers, 2016 to 2026). A primary or metastatic malignant neoplasm that affects the colon or rectum. "Although the role of SPOP in colorectal cancers is unclear, SPOP downregulation is observed in approximately 20–61% of colorectal cancer patients despite the rarity of SPOP mutations in colorectal cancer." (PMID 39540935, 2024). "SPOP downregulation has been linked to colorectal cancer (CRC), with its reduced mRNA or protein levels significantly associated with poor differentiation, distant metastasis, and advanced TNM stages." (PMID 39540935, 2024). "Currently, only one SPOP mutation has been found in a cohort of 45 colorectal cancer patients by the mutational landscape study of SPOP." (PMID 39540935, 2024). "Frequent SPOP mutation was found in various malignancies, such as prostate, breast, lung, gastric, and colorectal cancers." (PMID 36769824, 2023). "Similarly, reduced SPOP expression in colorectal cancer is significantly associated with adverse clinicopathological features, such as poor differentiation and increased hematogenous metastasis." (PMID 41122967, 2025). "Our previous studies found that TMEM160 is associated with poor prognosis in patients with colorectal cancer, as it can inhibit the ubiquitination and degradation of programmed death-ligand 1 (PD-L1) by competing with Speckle-type POZ protein (SPOP) to promote immune evasion and radioresistance." (PMID 40223081, 2025). "Importantly, although SPOP mutations are barely detected in colorectal cancer, SPOP downregulation at the mRNA or protein levels is frequently observed in 20–61% of colorectal cancer patients." (PMID 39540935, 2024). "Studies on SPOP mutation in other solid carcinomas is reported in follicular and papillary thyroid cancers, endometrial clear cell carcinoma, gynecological carcinosarcoma, lung cancer, and colorectal cancer." (PMID 29986747, 2018). "Retinoic acid-inducible gene-I (RIG-I) competes with SPOP for PD-L1 binding in colorectal cancer, inhibiting the ubiquitination of PD-L1 and contributing to tumor immune evasion." (PMID 39223632, 2024). "Cancer stem cell-derived exosomal miR-17-5p reduced SPOP expression and increased PD-L1 accumulation, leading to suppression of antitumor immunity in colorectal cancer cells." (PMID 36733484, 2023). "We collected a concentration series of SAXS data on the SPOP mutant R221C, which has been identified in melanoma and colorectal cancer." (PMID 36856266, 2023). "ILF3 has been reported to function as a critical regulator for the serine-glycine one-carbon (SGOC) pathway in colorectal cancer (CRC) via EGFR-ERK axis followed by E3 ligase speckle-type POZ protein (SPOP)-mediated poly-ubiquitination and degradation of ILF3." (PMID 34568427, 2021). "It was found that the down-regulated SPOP expression was significantly correlated to poor differentiation (P = 0.013) and advanced clinical stage (P = 0.002) in colorectal cancer." (PMID 34838022, 2021). "We suggested that demethylation of SPOP promoter region can be used as the novel epigenetic therapy for colorectal cancer." (PMID 28032859, 2016). "In this study, we found that hypermethylation of SPOP promoter induces the transcriptional repression and decreased cell apoptosis in colorectal cancer." (PMID 28032859, 2016). "In addition, miR-372/373 directly targeted SPOP and led to poor differentiation of colorectal cancer." (PMID 36769824, 2023). "Several studies have shown that SPOP expression is downregulated in some primary tumours, including gastric cancer, liver cancer, colorectal cancer, pancreatic cancer and non-small cell lung cancer, and low expression of SPOP is associated with poor prognosis in patients." (PMID 36474188, 2022). "Levels of the PI3K/Akt pathway have been found to be correlated with SPOP expression, which could inhibit colorectal cancer and osteosarcoma invasion by significantly reducing the levels of PI3K and p-Akt." (PMID 36474188, 2022).
colorectal cancer (continued). "Furthermore, as reported, a lower SPOP expression profile might serve as a potential biomarker for poorer prognosis in patients with colorectal cancer according to Kaplan-Meier survival curve analysis." (PMID 39074086, 2024). "On the contrary, if overexpressed SPOP in vitro, colorectal cancer cells can be dramatically repressed the proliferation and migration via EMT relative pathways, while this process can be reversed by knockdown of SPOP." (PMID 39074086, 2024). "In colorectal cancer (CRC) cells, ALDH2 competes with SPOP for binding to PD-L1, thereby inhibiting the degradation of PD-L1." (PMID 39223632, 2024).
breast carcinoma (17 papers, 2016 to 2025). "Genomic analysis of the SPOP locus in breast cancer reveals frequent instances of genomic loss or loss of heterozygosity." (PMID 40521202, 2025). "Little is known regarding the SPOP gene mutations in Chinese breast cancer patients so far, implying alternative mechanisms in breast cancer progression, particularly for TNBC and advanced cancer stages." (PMID 36115849, 2022). "Our findings could also be potentially expanded to other cancers, wherein SPOP is found to be mutated (endometrial and thyroid cancers) or its protein levels reduced (e.g., gastric, colon, and breast cancers)." (PMID 34322378, 2021). "In breast cancer, SPOP represents one of the highest loci for loss of heterozygosity." (PMID 27200299, 2016). "Thus, the high levels of ASCT2, coupled with the low levels of SPOP would cause an increased glutamine transportation to facilitate a high glutamine consumption in breast cancer tissues, providing mechanistic support of the notion that tumor tissues have a high glutamine consumption." (PMID 35641493, 2022). "However, a low mutation frequency of SPOP gene is found in breast cancer." (PMID 36115849, 2022). "A growing body of research has investigated the role of SPOP in breast cancer and gynecologic cancers, including endometrial, cervical, and ovarian cancers." (PMID 40521202, 2025). "CircXPO6 interacts with c-Myc to inhibit its ubiquitination and degradation by speckle-type POZ protein (SPOP), enhancing breast cancer cell migration and invasion." (PMID 40740236, 2025). "This study highlights the therapeutic potential of targeting the SPOP-Twist1 axis in breast cancer treatment strategies." (PMID 40521202, 2025). "In summary, the SPOP-SRC-3 axis serves as a crucial regulatory mechanism in breast cancer, with therapeutic interventions aimed at restoring this pathway potentially improving outcomes and overcoming resistance in patients." (PMID 40521202, 2025). "The SPOP-PR axis plays a critical role in breast cancer by regulating PR protein stability through ubiquitin-dependent degradation." (PMID 40521202, 2025). "Clinically, tumor tissues have higher levels of ASCT2, but lower levels of SPOP in breast cancer tissues, as compared to adjacent normal tissues." (PMID 40440083, 2024). "Upon glutamine deprivation, SPOP can auto-ubiquitylate and negatively regulate the uptake and metabolism of glutamine in breast cancer." (PMID 37190313, 2023). "In this study, we elucidate a tumor-suppressive role of SPOP in advanced breast cancer by negatively controlling TWIST1 stability." (PMID 36115849, 2022). "Clinically, SPOP is negatively correlated with the levels of TWIST1 in highly invasive breast carcinomas." (PMID 36115849, 2022). "Reduced SPOP expression, along with elevated TWIST1 levels, is associated with poor prognosis in advanced breast cancer patients, particularly those with metastatic triple-negative breast cancer (TNBC)." (PMID 36115849, 2022). "Breast cancer metastasis suppressor 1 (BRMS1), progesterone receptor (PR) and c-Myc have been indicated as direct targets of SPOP in breast cancer for ubiquitin-dependent proteasomal degradation." (PMID 36115849, 2022). "In the aggregate, these results suggest that the outcomes of SPOP on breast cancer malignancy are mediated, at least in part, by TWIST1." (PMID 36115849, 2022). "Taken together, ASCT2 appears to be a strong oncogenic protein, whereas SPOP is relatively a weak tumor suppressor in breast cancer cells." (PMID 35641493, 2022). "Higher expression of SPOP positively correlated with longer survival in TNBC or high-grade breast cancer patients, whereas patients with increased levels of TWIST1 were associated with poor prognosis." (PMID 36115849, 2022). "Taken together, we have linked SPOP to TWIST1 destabilization for its tumor suppressive functions such as inhibiting EMT and metastasis of breast cancer cells." (PMID 36115849, 2022).
breast carcinoma (continued). "In breast cancer tissues, an inverse correlation was found between SPOP and ASCT2, and breast cancer tissues have enhanced glutamine metabolism." (PMID 35641493, 2022). "The gene amplification of wild-type SPOP was detected in approximately 5% of breast cancer patients." (PMID 33023230, 2020). "Some researchers have indicated that SPOP acts as a tumor suppressor in endometrial prostate and breast cancers." (PMID 30607139, 2018). "Progesterone receptor, which contributes to the development of breast cancer, is found to function as a substrate of SPOP is this cancer type." (PMID 27200299, 2016). "However, in breast cancer, SPOP appears to promote tumor metastasis by degrading BRMS1 76, a key metastasis suppressor gene." (PMID 40521202, 2025). "This axis highlights a molecular pathway essential for maintaining PR homeostasis, and its disruption—such as through SPOP inactivation—may contribute to breast cancer progression." (PMID 40521202, 2025). "On the basis of the results of RNA pull down, mass spectrometry and RIP, we found that circLRBA could physically combine with SPOP in breast cancer cells." (PMID 41082269, 2025). "Moreover, SPOP and SLC1A5 levels are inversely associated in human breast cancer specimens, and lower SPOP and higher ASCT2 levels predict poorer patient survival." (PMID 37190313, 2023). "This notion of cell-type-specific regulation of protein degradation is further underpinned by the fact that we show in this manuscript that SPOP is dispensable for cMYC degradation in our cell models, whereas it has been reported to mediate cMYC turnover in prostate and breast cancers." (PMID 37622993, 2023). "In breast cancer cells, growth stimulation upon SPOP knockdown can be fully rescued by simultaneous ASCT2 knockdown seen both in vitro cell culture and in vivo xenograft tumor models, indicating a causal relationship between SPOP and ASCT2 in regulation of tumor growth." (PMID 35641493, 2022). "To evaluate the role of SPOP in growth and metastasis of breast cancer cells in vivo, we inoculated SPOP-knockdown (KD-SPOP) breast cancer cells or control (vehicle) cells into fat pads in the 4th mammary gland of nude mice and monitored xenograft tumor growth and metastasis." (PMID 36115849, 2022). "With its tumor suppressive function, SPOP may prevent breast cancer progression into the advanced stage, particularly in TNBC." (PMID 36115849, 2022). "The results indicate that as a mediator of TWIST1 destabilization, SPOP promotes metastasis of breast cancer cells and may serve as a potential target for personalized therapy and a clinical marker for disease prognosis." (PMID 36115849, 2022). "Interestingly, initial testing with a panel of breast cancer cell lines revealed an inverse correlation between SPOP and TWIST1." (PMID 36115849, 2022). "Importantly, orthotopic transplantation of SPOP knock-down breast cancer cells into the fat pad of the 4th mammary gland of nude mice resulted in enhanced lung metastasis compared to control cells treated with vehicle only." (PMID 36115849, 2022). "Searching for interacting proteins that may regulate TWIST1 by STRING Interaction Network analysis, we discovered a potential link between TWIST1 and SPOP, a less-known E3 ligase in the breast cancer field." (PMID 36115849, 2022). "In addition to kidney cancer, SPOP is reported to mediate ubiquitination and destabilization of breast cancer metastasis suppressor 1 (BRMS1) in breast cancer, thereby derepressing metastasis-associated genes." (PMID 27200299, 2016). "Thus SPOP may function as a tumor suppressor to inhibit breast cancer progression to advanced stages, including triple negative, positive lymph node status and high grade." (PMID 36115849, 2022). "More importantly, high SPOP/low ASCT2 predicts a better, whereas low SPOP/high ASCT2 predicts a worse survival of breast cancer patients." (PMID 40440083, 2024).
breast carcinoma (continued). "To determine expression correlation between SPOP and ASCT2, we used immunohistochemistry staining to measure the levels of SPOP and ASCT proteins in human breast cancer tissues, and their correlations with patient survival." (PMID 35641493, 2022). "The inverse correlation between SPOP and TWIST1 in breast carcinoma tissues and their functional interplay prompted us to address the regulatory mechanisms." (PMID 36115849, 2022). "To substantiate the correlation of SPOP and TWIST1 protein levels, we collected invasive ductal carcinoma tissues from Chinese breast cancer patients and adjacent normal tissues for analysis." (PMID 36115849, 2022). "Silencing SPOP significantly enhances EMT, which accelerates breast cancer cell migration and invasiveness in vitro and lung metastasis in vivo." (PMID 36115849, 2022). "In human breast cancer specimens, SPOP and ASCT2 levels are inversely correlated, whereas lower SPOP with higher ASCT2 predicts a worse patient survival." (PMID 35641493, 2022). "In the current study, we found that SPOP destabilizes TWIST1 through the ubiquitin proteasomal pathway, thereby inhibiting EMT and breast cancer metastasis in vitro and in vivo." (PMID 36115849, 2022). "Furthermore, re-expression of SPOP effectively suppresses SRC-3-driven oncogenic signaling and tumorigenesis, highlighting its role as a tumor suppressor in breast cancer." (PMID 40521202, 2025). "The SPOP-TWIST1 pathway disclosed in this study may provide potentially novel therapeutics and prognostic markers for advanced breast cancer patients." (PMID 36115849, 2022). "Moreover, lower SPOP and higher TWIST1 are correlated with poor prognosis in breast cancer patients." (PMID 36115849, 2022). "Furthermore, the protein levels of SPOP and ASCT2 is inversely correlated in breast cancer tissues; and lower SPOP coupled with higher ASCT2 predicts a poor patient survival, whereas higher SPOP coupled with lower ASCT2 predicts a better patient survival." (PMID 35641493, 2022). "Numerous studies indicate that SPOP suppresses tumor progress in many human malignancies such as prostate, lung, gastric, colon, and liver cancers, but not well studied in breast cancers." (PMID 36115849, 2022). "To determine whether SPOP could affect EMT, we silenced SPOP in both BT549 and T47D breast cancer lines and examined the effects on E-cadherin, Vimentin and N-cadherin by Western blotting." (PMID 36115849, 2022). "Furthermore, the inverse expression patterns of SPOP and TWIST1 were verified by immunohistochemistry analysis of breast cancer tissues." (PMID 36115849, 2022). "How the tumor-suppressive E3 ligase, speckle-type POZ protein (SPOP), regulates TWIST1 in breast cancer remains unknown." (PMID 36115849, 2022). "SPOP functions for tumorigenesis in breast cancer are not yet known." (PMID 36115849, 2022). "Furthermore, we demonstrated that circLRBA could interact competitively with the E3 ubiquitin ligase SPOP to hinder the binding between SPOP and Twist1 and enhance the transcriptional activation of PD‐L1, thus promoting the EMT, chemoimmunotherapy resistance and metastasis of breast cancer." (PMID 41082269, 2025).
kidney cancer (16 papers, 2016 to 2025). Primary or metastatic malignant neoplasm involving the kidney. "SPOP can suppress tumorigenesis in various human malignancies, including lung, prostate, colon, gastric, and liver cancers; however, there is also evidence revealing that SPOP exhibits oncogenic functions in kidney cancer." (PMID 37382594, 2023). "SPOP acts a key regulatory hub in kidney cancer by degrading several tumor suppressors, including PTEN, which exhibits low levels in ccRCC patient samples, and SPOP-mediated degradation of PTEN promotes tumor cell proliferation in A498 ccRCC cells." (PMID 34021128, 2021). "Due to the oncogenic role of SPOP in kidney cancer, SPOP inhibitors are necessary for the suppression of SPOP to treat kidney cancer." (PMID 31901237, 2020). "SPOP high expression occurs in 99% of clear cell renal cell carcinoma (ccRCC), the most prevalent type of kidney cancer." (PMID 27200299, 2016). "Interestingly, the small molecule SPOP inhibitor SPOP-IN-6b (6b) was developed for treating kidney cancer where SPOP exerts an oncogenic function, and it was further upgraded to SPOP-i-6lc (6lc) through medicinal chemistry optimization." (PMID 41148213, 2025). "While SPOP’s roles in prostate and kidney cancers are well established, its function in melanoma remains unclear." (PMID 41148213, 2025). "It has been shown that in kidney cancer, SPOP promoted the ubiquitination and degradation of DAXX." (PMID 34680332, 2021). "Furthermore, ectopic expression of SPOP decreased SUFU protein levels in the kidney cancer cell line A498 and ovarian cancer cell line SKOV3, and siSPOP showed the opposite results, suggesting the physiological significance of this regulation in carcinogenesis." (PMID 34021128, 2021). "However, several studies revealed that SPOP exhibited oncogenic function in kidney cancer, suggesting that SPOP could exert its biological function in a cancer type-specific manner." (PMID 31901237, 2020). "A recent study showed that SPOP increases ubiquitination of the LATS1 protein and promotes its degradation in kidney cancer." (PMID 37684641, 2023). "Additionally, hypoxia is sufficient to induce the cytoplasmic accumulation of SPOP, which promotes the ubiquitin-mediated degradation of several tumor suppressors (Daxx, PTEN, DUSP7, and Gli2) and leads to tumorigenesis in kidney cancer." (PMID 31901237, 2020). "Interestingly, ACE2 protein levels are decreased by SPOP shRNA knockdown in human UMRC kidney cancer cells, suggesting that SPOP prevents, but not promotes, ACE2 protein from degradation." (PMID 37608279, 2023).